FSD1L (fibronectin type III and SPRY domain containing 1 like)
Synonyms: CCDC10; CSDUFD1; FSD1CL; FSD1NL; MIR1
Tractability: Antibody: the Human Protein Atlas places it where antibodies can reach. PROTAC: ubiquitination databases record sites on it; its protein half-life has been measured.
Gene: Protein-coding gene on chromosome 9 (105,447,796 to 105,552,433, forward strand). Ensembl gene ENSG00000106701.
Subcellular location (Human Protein Atlas): Plasma membrane; Golgi apparatus; Vesicles
Genetic constraint (gnomAD): Loss-of-function variants: 11 observed, 21.72 expected, observed/expected ratio (o/e) 0.51, 90% interval 0.32 to 0.84. The upper end of that interval is the gene's LOEUF score, 0.84, which puts it in group 3 of 6, group 1 being the genes least tolerant of losing a copy. Missense variants: 204 observed, 260.83 expected, observed/expected ratio (o/e) 0.78, 90% interval 0.7 to 0.88. Synonymous variants: 81 observed, 83.25 expected, observed/expected ratio (o/e) 0.97, 90% interval 0.81 to 1.17.
Homologues: Orthologues: macaque FSD1L (98% identical), rabbit FSD1L (92% identical), dog FSD1L (90% identical), rat Fsd1l (89% identical), mouse Fsd1l (89% identical), guinea pig FSD1L (84% identical), pig FSD1L (83% identical), chimpanzee FSD1L (77% identical), tropical clawed frog fsd1l (76% identical), zebrafish fsd1l (68% identical). Paralogues in human: FSD1 (56% identical), CMYA5 (22% identical), FSD2 (19% identical).
Diseases named in the same sentence as FSD1L in open-access papers:
FSD1L is named in the same sentence as 8 diseases in open-access papers, as found by Europe PMC text mining. Sharing a sentence is not in itself a finding about the gene and the disease. The quoted sentences say what the papers report.
Hyperglycemia (1 paper, 2024). An increased concentration of glucose in the blood. "Also, a group of 5-year-old children exposed to hyperglycemia during the gestational stage was studied, and a decrease was found in the methylation of the gene fibronectin type III and SPRY domain-containing 1 like (FSD1L)." (PMID 38397953, 2024).
FSD1L also shares sentences with these, for which no sentence is quoted: cancer (1 paper); hepatocellular carcinoma (1); L1 syndrome (1); neurodevelopmental disorder (1); ovarian carcinoma (1); retinitis pigmentosa (1); tumor (1).